ZNF160 (zinc finger protein 160)
Description:
May be involved in transcriptional regulation.
Synonyms: HKr18; KIAA1611; HZF5; F11; KR18; FLJ00032
Tractability: PROTAC: UniProt records ubiquitination sites on it; ubiquitination databases record sites on it.
Gene: Protein-coding gene on chromosome 19 (53,064,884 to 53,103,434, reverse strand). Ensembl gene ENSG00000170949.
Subcellular location: Nucleus
Subcellular location (Human Protein Atlas): Nuclear speckles; Cytosol
Pathways (Reactome):
Gene expression (Transcription): Generic Transcription Pathway
Gene Ontology:
Molecular function: DNA-binding transcription factor activity, RNA polymerase II-specific; RNA polymerase II cis-regulatory region sequence-specific DNA binding; sequence-specific double-stranded DNA binding
Biological process: hemopoiesis; regulation of transcription by RNA polymerase II; regulation of DNA-templated transcription
Cellular component: nucleus
Genetic constraint (gnomAD): Loss-of-function variants: 8 observed, 13.12 expected, observed/expected ratio (o/e) 0.61, 90% interval 0.36 to 1.1. The upper end of that interval is the gene's LOEUF score, 1.1, which puts it in group 4 of 6, group 1 being the genes least tolerant of losing a copy. Missense variants: 827 observed, 1,022.1 expected, observed/expected ratio (o/e) 0.81, 90% interval 0.76 to 0.86. Synonymous variants: 286 observed, 341.27 expected, observed/expected ratio (o/e) 0.84, 90% interval 0.76 to 0.92.
Homologues: Orthologues: chimpanzee ZNF160 (99% identical), macaque ZNF160 (98% identical), mouse Zfp160 (52% identical), rat Zfp160 (52% identical), zebrafish znf646 (23% identical), zebrafish si:dkey-89b17.4 (22% identical), Drosophila melanogaster zf30C (22% identical), Drosophila melanogaster CG18011 (20% identical), zebrafish znf576.1 (20% identical), Drosophila melanogaster CG6791 (19% identical), Drosophila melanogaster CG30020 (17% identical), Caenorhabditis elegans ztf-15 (16% identical), and 23 more. Paralogues in human: ZNF665 (66% identical), ZNF347 (65% identical), ZNF845 (52% identical), ZNF91 (51% identical), ZNF208 (48% identical), ZNF107 (47% identical), ZNF729 (46% identical), ZNF99 (46% identical), ZNF184 (45% identical), ZNF420 (45% identical), ZNF84 (44% identical), ZNF569 (40% identical), and 24 more.
Diseases named in the same sentence as ZNF160 in open-access papers:
ZNF160 is named in the same sentence as 7 diseases in open-access papers, as found by Europe PMC text mining. Sharing a sentence is not in itself a finding about the gene and the disease. The quoted sentences say what the papers report.
Arthritis (1 paper, 2021). Inflammation of a joint. "Therefore, further investigation should be conducted to verify the accuracy of a combined analysis of ZNF160 expression level and immune infiltration profiles in patients with arthritis." (PMID 34670585, 2021).
breast carcinoma (1 paper, 2016). "Among the genes down-regulated in this GO term were transcriptional repressors of immune system such as ZFAT (Zinc Finger Protein 406, FC = 2.4); BRCA2 (Breast Cancer 2, Early Onset, FC = 3.2), and ZNF160 (Zinc Finger Protein 160, FC = 2.5)." (PMID 27427759, 2016).
leukoplakia (1 paper, 2023). A white patch or plaque on a mucous membrane that cannot be characterized clinically or pathologically as any other disease. "We found 4 genes (LY75, ZNF83, ZNF160, ZNF331) common in leukoplakia and OSCC, while 9 genes appeared only in OSCC, suggesting their role in disease advancement." (PMID 37245006, 2023).
oropharyngeal cancer (1 paper, 2015). Carcinoma, predominantly squamous cell, arising from the epithelial cells of the oropharynx. "All but ZNF14 are located on the 19q13 locus, which was shown to be epigenetically silenced in oropharyngeal cancer, supporting the hypothesis that ZNF160, ZNF420, ZNF585B, and ZNF71 are epigenetically regulated in a coordinated fashion." (PMID 26544568, 2015).
tumor (2 papers, 2015 to 2017). "Of all remaining five ZNF protein genes, ZNF14, ZNF160, ZNF71, ZNF420 and ZNF585B, DNA methylation was significantly higher in tumor samples, as compared to normal controls." (PMID 26544568, 2015). "For example, TFs, such as ASH1L, CFLAR, HMGB3, ZNF160 and MATR3, displayed opposite behaviors on some cytokines; inflammatory factors; nuclear and tumor factors, such as IL-2, IL-6, NF-κB, and Irf3; immunogenic nucleic acids; papillomavirus E7/E6; caspase-3/caspase-8; Toll-like receptor; and so on." (PMID 28719625, 2017).
ZNF160 also shares sentences with these, for which no sentence is quoted: Alzheimer disease (1 paper); head and neck cancer (1).